BACE1 (beta-secretase 1)
Description:
Responsible for the proteolytic processing of the amyloid precursor protein (APP). Cleaves at the N-terminus of the A-beta peptide sequence, between residues 671 and 672 of APP, leads to the generation and extracellular release of beta-cleaved soluble APP, and a corresponding cell-associated C-terminal fragment which is later released by gamma-secretase. Cleaves CHL1 (By similarity).
Synonyms: ASP2; BACE; HSPC104
Tractability: Small molecule: a drug acting on it is in phase 2 or 3 trials; a structure with a bound ligand is known; a high-quality ligand is known; it has a high-quality binding pocket; it belongs to a druggable protein family. Antibody: UniProt places it where antibodies can reach, with high confidence; its Gene Ontology location is reachable by antibodies, with high confidence; UniProt predicts a signal peptide or a membrane-spanning region; the Human Protein Atlas places it where antibodies can reach. PROTAC: UniProt records ubiquitination sites on it; ubiquitination databases record sites on it; its protein half-life has been measured; a small molecule that binds it is known.
Target class: Aspartic protease; Aspartic protease A1A subfamily; Protease; Enzyme; Aspartic protease AA clan
Chemical probes: AM-6494 (high quality), CHEMBL401473, CHEMBL576258, Lanabecestat (high quality), PD080777, PD081360, PD082353, PD082534, PD082702, PD083712, PD083994, PD085058, VERUBECESTAT, atabecestat (high quality)
Gene: Protein-coding gene on chromosome 11 (117,285,232 to 117,316,286, reverse strand). Ensembl gene ENSG00000186318.
Subcellular location: Cell membrane; Golgi apparatus, trans-Golgi network; Endoplasmic reticulum; Endosome; Cell surface; Cytoplasmic vesicle membrane; Membrane raft; Lysosome; Late endosome; Early endosome; Recycling endosome; Cell projection, axon; Cell projection, dendrite
Subcellular location (Human Protein Atlas): Plasma membrane
Pathways (Reactome):
Metabolism of proteins: Amyloid fiber formation
Gene Ontology:
Molecular function: amyloid-beta binding; aspartic-type endopeptidase activity; endopeptidase activity; enzyme binding; peptidase activity; protein binding; protein serine/threonine kinase binding; beta-aspartyl-peptidase activity
Biological process: amyloid-beta formation; amyloid-beta metabolic process; membrane protein ectodomain proteolysis; positive regulation of neuron apoptotic process; protein processing; proteolysis; amyloid fibril formation; amyloid precursor protein catabolic process; cellular response to amyloid-beta; cellular response to copper ion; cellular response to manganese ion; detection of mechanical stimulus involved in sensory perception of pain; modulation of chemical synaptic transmission; prepulse inhibition; presynaptic modulation of chemical synaptic transmission; regulation of neuron apoptotic process; response to insulin-like growth factor stimulus; response to lead ion; signaling receptor ligand precursor processing; swimming behavior
Cellular component: cell surface; cytoplasmic vesicle membrane; early endosome; endoplasmic reticulum; endosome; Golgi apparatus; late endosome; lysosome; multivesicular body; plasma membrane; recycling endosome; trans-Golgi network; endoplasmic reticulum lumen; endosome membrane; Golgi-associated vesicle lumen; membrane; membrane raft; axon; cytoplasmic vesicle; dendrite; hippocampal mossy fiber to CA3 synapse; neuronal cell body; presynapse; synaptic vesicle
Genetic constraint (gnomAD): Loss-of-function variants: 18 observed, 47.97 expected, observed/expected ratio (o/e) 0.38, 90% interval 0.26 to 0.56. The upper end of that interval is the gene's LOEUF score, 0.56, which puts it in group 2 of 6, group 1 being the genes least tolerant of losing a copy. Missense variants: 497 observed, 651.64 expected, observed/expected ratio (o/e) 0.76, 90% interval 0.71 to 0.82. Synonymous variants: 226 observed, 250.63 expected, observed/expected ratio (o/e) 0.9, 90% interval 0.81 to 1.01.
Homologues: Orthologues: chimpanzee BACE1 (99% identical), macaque BACE1 (99% identical), rabbit BACE1 (98% identical), guinea pig BACE1 (97% identical), mouse Bace1 (96% identical), rat Bace1 (96% identical), pig BACE1 (93% identical), dog BACE1 (86% identical), tropical clawed frog bace1 (78% identical), zebrafish bace1 (28% identical), Drosophila melanogaster CG17134 (22% identical), Drosophila melanogaster CG6508 (20% identical), and 12 more. Paralogues in human: BACE2 (46% identical), PGA3 (23% identical), PGA4 (23% identical), PGA5 (23% identical), CTSD (23% identical), CTSE (22% identical), PGC (21% identical), REN (20% identical), NAPSA (20% identical).
Diseases named in the same sentence as BACE1 in open-access papers:
BACE1 is named in the same sentence as 193 diseases in open-access papers, as found by Europe PMC text mining. Sharing a sentence is not in itself a finding about the gene and the disease. The quoted sentences say what the papers report.
Alzheimer disease (611 papers, 2005 to 2026). A progressive, neurodegenerative disease characterized by loss of function and death of nerve cells in several areas of the brain leading to loss of cognitive function such as memory and language. "Recent research affirmed the presence of a corresponding relation between the activity of BACE1 and the production of Aβ, the latter represents a central pathological hallmark of Alzheimer’s disease." (PMID 40072673, 2025). "Probably, this strategy, as well as a decrease in APP or BACE1 (which encodes β-secretase) expression, will be helpful in treating Alzheimer’s disease." (PMID 40650152, 2025). "We discovered activating expression of the Alzheimer’s disease associated β-site amyloid precursor protein cleaving enzyme 1 (BACE1) led to a significant increase in brain metastasis." (PMID 40601773, 2025). "β-secretase 1 (BACE1), known for its role in amyloid-β production associated with Alzheimer’s disease (AD), has also been suggested to be elevated in patients with Type 2 diabetes mellitus (T2DM)." (PMID 40507910, 2025). "Chronic opioid use also increases amyloid-beta (Aβ) production, a hallmark of Alzheimer’s disease, by elevating amyloid precursor protein and BACE1 expression, further enhancing neuroinflammation." (PMID 40657909, 2025). "The deposition of toxic aggregated amyloid-β (Aβ), resulting from continuous cleavage of amyloid precursor protein (APP) by β-site APP cleaving enzyme 1 (BACE1) and γ-secretase, is a key pathogenic event in Alzheimer's disease (AD)." (PMID 40814010, 2025). "BACE-1, a membrane-associated aspartyl protease, plays a central role in the generation of amyloid-β peptide, making it a primary drug target for Alzheimer’s disease." (PMID 38999999, 2024). "BACE1 is also associated with Alzheimer’s disease via the literature and in the GO, KEGG and DISEASES database and in this study we show it is a predicted target of bortezomib and carfilzomib (based on SEA search)." (PMID 38576795, 2024). "The MD transcriptome included high expression of Alzheimer’s disease risk genes (App, Mapt, Bace1, Apoe) and the nerve growth factor (NGF) receptor (Ngfr)." (PMID 38598837, 2024). "TUFM has been implicated in Alzheimer’s disease (AD) pathology by regulating BACE1 translation, apoptosis, and Tau phosphorylation." (PMID 39478699, 2024). "The β-secretase-1 enzyme (BACE-1) performs a key role in the production of beta-Amyloid protein (Aβ), which is associated with the development of Alzheimer’s disease (AD)." (PMID 37175873, 2023). "In recent studies, inhibition of microglial BACE1, which regulates microglial gene signatures associated with phagocytosis, has been suggested as a superior strategy for Alzheimer’s disease." (PMID 37552127, 2023). "BACE1 is the main β-secretase in the pathogenic process of Alzheimer’s disease, which is believed to be a rate-limiting step of Aβ production." (PMID 36555791, 2022). "Potential motor deficits were also seen in Alzheimer patients and elderly individuals with high risk for Alzheimer’s disease that were treated in phase 3 studies with a BACE1 inhibitor." (PMID 34958451, 2022). "BACE1 initiates production of β-amyloid peptides (Aβ), which is associated with cognitive dysfunction in Alzheimer’s disease (AD) due to abnormal oligomerization and aggregation." (PMID 34158621, 2021). "Cleavage of APP by BACE1 and subsequent cleavage by γ-secretase leads to the generation of Aβ peptides that form Aβ plaques that are a pathological hallmark of Alzheimer’s disease." (PMID 33722254, 2021). "There are a number of clinical studies that have reported a respectable diagnostic performance of CSF BACE1 activity and concentration in differentiating symptomatic Alzheimer’s disease patients from cognitively healthy controls." (PMID 33578866, 2021). "The Aβs, from the amyloid β precursor protein cleaved by BACE1, are associated with the pathogenesis of Alzheimer’s disease." (PMID 33670685, 2021).
Alzheimer disease (continued). "BACE1 encodes the β-secretase enzyme, which has been shown to be a driver of Alzheimer’s disease-associated pathology." (PMID 33946840, 2021). "The proteolytic processing of amyloid precursor protein (APP) by β-secretase (BACE1) and γ-secretase releases amyloid-β peptide (Aβ), which deposits in amyloid plaques and contributes to the initial causative events of Alzheimer’s disease (AD)." (PMID 33804171, 2021). "To investigate if NHE6/Slc9a6 deficiency contributes to APP processing by BACE1 in neurons, we used primary neurons derived from AppSwe (Tg2576) mice, an Alzheimer’s disease (AD) mouse model that overexpresses human APP with the ‘Swedish’ mutation." (PMID 34617884, 2021). "When tested against BACE1 (β-site Amyloid precursor protein Cleaving Enzyme type 1), an enzyme implicated in Alzheimer’s disease, compound 40 was about 12- to 30-fold less active as an BACE1 inhibitor compared to cathepsins D and E." (PMID 32397127, 2020). "Proteases BACE1 (β-secretases) enzymes have been recognized as a promising target associated with Alzheimer's disease (AD)." (PMID 32462027, 2020). "For example, Alzheimer's disease‐linked protease β‐site APP‐cleaving enzyme (BACE1), which has fundamental functions in the brain, is highly expressed in neurons, but not in astrocytes, microglia, or oligodendrocytes." (PMID 32954517, 2020). "Seizure protein 6 (SEZ6) is required for the development and maintenance of the nervous system, is a major substrate of the protease BACE1 and is linked to Alzheimer's disease (AD) and psychiatric disorders, but its molecular functions are not well understood." (PMID 32567721, 2020). "For instance, BACE1 inhibitors and anti-amyloid-β biologics reduce amyloid-β deposits in the brain that are thought to be a cause of Alzheimer’s disease, the most prevalent form of dementia." (PMID 32670015, 2020). "Kang and coworkers also prepared an elaborate series of sulfonated-4-aminochalcones and tested their activities against the β-secretase (BACE1), an enzyme linked to the onset of Alzheimer’s disease." (PMID 33213087, 2020). "A molecular imaging probe to fluorescently image the β-site of the amyloid precursor protein (APP) cleaving enzyme 1 (BACE1) and cathepsin D (CatD) enzymes associated with Alzheimer’s disease (AD) was designed and synthesized." (PMID 31936569, 2020). "Currently, in humans, BACE1 is known to increase risk of Alzheimer’s disease with increased expression." (PMID 29404214, 2018). "β-Site amyloid precursor protein cleaving enzyme 1 (BACE1) is required for the production of β-amyloid (Aβ), one of the major pathogenic molecules of Alzheimer’s disease (AD), and is therefore being actively pursued as a drug target for AD." (PMID 30079376, 2018). "Amyloid precursor protein (APP) is cleaved by β-site amyloid precursor protein-cleaving enzyme 1 (BACE1) to produce β-amyloid (Aβ), a critical pathogenic peptide in Alzheimer’s disease (AD)." (PMID 28109317, 2017). "BACE1 enzyme is essential for the generation of amyloid-β, the hallmark neuropathological lesions in Alzheimer’s disease brain." (PMID 26784894, 2016). "Beta-site APP-cleaving enzyme 2, BACE2, is an aspartyl protease commonly associated with BACE1, a related homolog responsible for amyloid processing in the brain and strongly implicated in Alzheimer’s disease." (PMID 26840340, 2016). "β-Secretase 1 (BACE1) is implicated in Alzheimer’s disease as the enzyme responsible for the rate-limiting step in β-amyloid (Aβ) production." (PMID 27138913, 2016). "For example, translation of β-site APP-cleaving enzyme 1 (BACE1), which is implicated in Alzheimer's disease (AD) progression, is regulated through uORFs." (PMID 28083147, 2016). "Translation of the mRNA encoding β-site APP cleaving enzyme 1 (BACE1) is increased by amyloid-β42action on cultured neurons (Sadleiret al., 2014;Mamadaet al., 2015) and in an Alzheimer’s disease mouse model (Caccamoet al., 2015)." (PMID 27524794, 2016).
Alzheimer disease (continued). "Previous data have implicated the BACE-1 protein as a central player in the pathogenesis of Alzheimer's disease." (PMID 27294139, 2016). "As a promising therapeutic target for the treatment of Alzheimer’s disease, understanding the detailed mechanism underlying the pH dependence of BACE-1 dynamics and enzymatic activity is imperative for structure-based drug design." (PMID 26506513, 2015). "The β-secretase called BACE1 is a membrane-associated protease that initiates the generation of amyloid β-protein, a key event in Alzheimer’s disease." (PMID 26464978, 2015). "For example an antisense transcript specific for the β-site APP-cleaving enzyme 1 gene (BACE1) encodes for an enzyme which has an important role in progression of Alzheimer’s disease." (PMID 25888968, 2015). "The β-secretase called BACE1 is a membrane-associated protease that initiates the generation of amyloid β-protein (Aβ), a key event in Alzheimer’s disease (AD)." (PMID 26464978, 2015). "Though BACE2 is also expressed in the brain, some reports revealed the protective effect of the enzyme towards Alzheimer's disease, by reducing the pathogenic forms of Aβ being produced within the cells that expressed both BACE1 and BACE2." (PMID 25254246, 2014). "Proteolytic cleavage of amyloid precursor protein by β-secretase (BACE1) is a key step in generating the N-terminal of β-amyloid (Aβ), which further forms into amyloid plaques that are considered as the hallmark of Alzheimer’s disease." (PMID 23681056, 2013). "The miR-29 family of miRNAs have target sites on BACE1 mRNA and loss of this cluster is negatively correlated with BACE1 expression in a subset of sporadic Alzheimer's disease cases." (PMID 24133413, 2013). "The gene β-site amyloid precursor protein (APP)-cleaving enzyme (BACE1) has been associated with Alzheimer’s disease (AD)." (PMID 24179440, 2013). "The beta site amyloid precursor protein cleaving enzyme 1, BACE1 (β-secretase), has been implicated in Alzheimer’s disease pathogenesis because it generates amyloid β-peptide from its precursor protein." (PMID 23720653, 2013). "It was reported that increased expression of either BC200 or an antisense transcript of the b-secretase-1 (BACE1) gene had been implicated in the progression of Alzheimer's disease." (PMID 21473757, 2011). "The BACE1 gene encodes the beta-site APP-cleaving enzyme 1 and has been associated with Alzheimer's disease (AD)." (PMID 20849576, 2010). "We illustrate these functions with real examples in Alzheimer's disease, e.g. a meta-analysis of the potential interaction between a BACE1 polymorphism and APOE4: SF = 2.5, 95% confidence interval: 1.5–4.2; p = 0.0001." (PMID 19527493, 2009). "While Bace1 is mainly associated with amyloid-β (Aβ) production in Alzheimer’s disease, its structural homology to Bace2 suggests that its inhibition may also impact melanin synthesis." (PMID 40286213, 2025). "Furthermore, silencing of lncRNA XIST reduced the Alzheimer’s disease-associated alteration of BACE1 via miR-124." (PMID 41245147, 2025). "BACE1 is an aspartic-acid protease that plays a critical role in the production of β-amyloid peptides, which accumulate to form amyloid plaques—a hallmark of Alzheimer’s disease pathology." (PMID 40795814, 2025). "Specifically, the challenges in Alzheimer’s disease (AD) trials, where the failure of several β-secretase 1 (BACE1) inhibitors demonstrates the risk of targeting a surrogate biomarker too late in the disease course, underscoring the necessity of early intervention in FTD." (PMID 41283303, 2025). "Furthermore, elevated serum levels of BACE-1 have been associated with cognitive decline in Alzheimer’s disease." (PMID 40291844, 2025). "Alzheimer's disease (AD) is associated with AChE and BACE1 enzymes." (PMID 40041377, 2025).